MIR223HG (MIR223 host gene)
Synonyms: linc-223
Gene: Long non-coding RNA gene on chromosome X (66,012,419 to 66,020,430, forward strand). Ensembl gene ENSG00000274536.
Gene Ontology:
Cellular component: RISC complex
Diseases named in the same sentence as MIR223HG in open-access papers:
MIR223HG is named in the same sentence as 2 diseases in open-access papers, as found by Europe PMC text mining. Sharing a sentence is not in itself a finding about the gene and the disease. The quoted sentences say what the papers report.
acute myeloid leukemia (1 paper, 2024). Acute myeloid leukemia (AML) is a group of neoplasms arising from precursor cells committed to the myeloid cell-line differentiation. "MIR223HG, acting as a competing endogenous RNA, inhibited acute myeloid leukemia progression by inducing IRF4 expression." (PMID 38914679, 2024).
MIR223HG also shares sentences with these, for which no sentence is quoted: ovarian carcinoma (1 paper).